WDR12 (WD repeat domain 12)
Description:
Component of the PeBoW complex, which is required for maturation of 28S and 5.8S ribosomal RNAs and formation of the 60S ribosome.
Synonyms: YTM1; FLJ10881
Tractability: Small molecule: a structure with a bound ligand is known. Antibody: the Human Protein Atlas places it where antibodies can reach. PROTAC: UniProt records ubiquitination sites on it; ubiquitination databases record sites on it; its protein half-life has been measured.
Gene: Protein-coding gene on chromosome 2 (202,874,261 to 203,014,798, reverse strand). Ensembl gene ENSG00000138442.
Subcellular location: Nucleus, nucleolus; Nucleus, nucleoplasm
Subcellular location (Human Protein Atlas): Cytosol; Plasma membrane; Nucleoli
Pathways (Reactome):
Metabolism of RNA: Major pathway of rRNA processing in the nucleolus and cytosol
Gene Ontology:
Molecular function: protein binding; ribonucleoprotein complex binding
Biological process: maturation of 5.8S rRNA from tricistronic rRNA transcript (SSU-rRNA, 5.8S rRNA, LSU-rRNA); maturation of LSU-rRNA from tricistronic rRNA transcript (SSU-rRNA, 5.8S rRNA, LSU-rRNA); regulation of cell cycle; ribosomal large subunit biogenesis; rRNA processing; ribosome biogenesis
Cellular component: nucleolus; nucleoplasm; PeBoW complex; preribosome, large subunit precursor; nucleus
Genetic constraint (gnomAD): Loss-of-function variants: 33 observed, 48.92 expected, observed/expected ratio (o/e) 0.67, 90% interval 0.51 to 0.9. The upper end of that interval is the gene's LOEUF score, 0.9, which puts it in group 3 of 6, group 1 being the genes least tolerant of losing a copy. Missense variants: 387 observed, 417.39 expected, observed/expected ratio (o/e) 0.93, 90% interval 0.85 to 1.01. Synonymous variants: 129 observed, 148.17 expected, observed/expected ratio (o/e) 0.87, 90% interval 0.75 to 1.01.
Homologues: Orthologues: rabbit WDR12 (97% identical), pig WDR12 (96% identical), guinea pig WDR12 (96% identical), chimpanzee WDR12 (96% identical), dog WDR12 (95% identical), macaque WDR12 (94% identical), mouse Wdr12 (94% identical), rat Wdr12 (93% identical), tropical clawed frog wdr12 (82% identical), zebrafish wdr12 (78% identical), Drosophila melanogaster CG6724 (41% identical), Caenorhabditis elegans wdr-12 (30% identical). Paralogues in human: WDR37 (25% identical).
Diseases named in the same sentence as WDR12 in open-access papers:
WDR12 is named in the same sentence as 35 diseases in open-access papers, as found by Europe PMC text mining. Sharing a sentence is not in itself a finding about the gene and the disease. The quoted sentences say what the papers report.
atherosclerosis (3 papers, 2016 to 2022). A disease characterized by the build-up of fatty material and calcium deposition in the arterial wall resulting in partial or complete occlusion of the arterial lumen. "Subsequently, the WDR12 gene on chromosome 2 harbouring the SNP rs7582720 encode for a ribosome biogenesis protein involved in cell proliferation which might play a role in the later event of atherosclerosis." (PMID 35379196, 2022).
glioblastoma (3 papers, 2020 to 2022). The most malignant astrocytic tumor (WHO grade IV). "High levels of WDR12 are associated with glioblastoma progression and poor prognosis." (PMID 34868955, 2021). "Another study that correlated glioblastoma with the overexpression of WDR12 demonstrated that the knockdown of WDR12 promoted apoptosis and inhibited the proliferation of tumor cells." (PMID 36726716, 2022). "Moreover, WDR12 was correlated with tumor progression in other human cancers including hepatocellular carcinoma and glioblastoma, and was studied as a target for natural anticancer products in the breast cancer model." (PMID 36726716, 2022). "Together, our results suggest that WDR12 is crucial for ribosome biogenesis in GSCs, and is thus a potential target for GSC-directed therapy of glioblastoma." (PMID 34868955, 2021). "It is worth noting that in this study, 8 (ACTR3, ARF4, PGRMC1, RPS23, WDR12, ACTR2, SIAH1, and RPS27L) of 12 hub genes are related to cancers, such as lung cancer, epithelial ovarian cancer, gastric cancer, glioblastoma, breast cancer, and esophageal cancer." (PMID 33391181, 2020).
lung carcinoma (3 papers, 2020 to 2021). "Candidate genes ACTR3, ARPC5, and HNRNPK were highly expressed in almost all types of lung cancer immune cells, while RAB13, PA2G4, and WDR12 were found to be less abundant in the majority of myeloid populations in lung cancer." (PMID 34868230, 2021).
myocardial infarction (3 papers, 2015). Gross necrosis of the myocardium, as a result of interruption of the blood supply to the area, as in coronary thrombosis. "In a recent genome-wide association study, WD-repeat domain 12 (WDR12) was associated with early-onset myocardial infarction (MI)." (PMID 25915632, 2015).
coronary artery disease (2 papers, 2015 to 2017). "Still, despite being statistically independent, we cannot exclude that the association we observe in humans could be a consequence of coronary heart disease, especially since knock-down of WDR12 has been shown to affect cholesterol metabolism." (PMID 25915632, 2015).
glioma (2 papers, 2021). A benign or malignant brain and spinal cord tumor that arises from glial cells (astrocytes, oligodendrocytes, ependymal cells). "Together, these results suggest that WDR12 is highly expressed in GBMs and associated with the malignant progression of gliomas." (PMID 34868955, 2021). "Importantly, high expression of WDR12 was associated with poor survival in all gliomas, whether high- or low-grade." (PMID 34868955, 2021). "To evaluate the clinical relevance of WDR12 in glioma and GBM, we analyzed the REMBRANDT and Gravendeel brain neoplasia databases." (PMID 34868955, 2021). "Interfering with the expression of WDR12 can inhibit the cell cycle, thereby inhibiting glioma." (PMID 34712323, 2021). "Immunohistochemically (IHC) staining with WDR12 antibody in a human glioma tissue microarray showed that both the intensity of WDR12 staining and the percentage of WDR12 positive cells were strongly increased in high-grade gliomas compared to low-grade gliomas." (PMID 34868955, 2021). "In our study, we found that WDR12 is significantly upregulated in glioma and GBM, and is associated with poor outcomes of brain tumors, indicating that WDR12 may be a prognostic marker in glioma and GBM." (PMID 34868955, 2021). "Moreover, the expression of WDR12 was significantly inversely correlated with survival of both gliomas and GBMs." (PMID 34868955, 2021). "Glioma databases analysis shows a strong positive correlation between the expression of WDR12 and multiple stem cell markers, suggesting that tumors with high levels of WDR12 may be enriched in GSCs." (PMID 34868955, 2021). "Additionally, glioma patients with high levels of WDR12 showed increased recurrence." (PMID 34868955, 2021). "In our previous mass spectrometry screen, we identified a series of proteins, including WDR12, that were highly expressed in glioma stem-like cells (GSCs) compared to those in non-stem tumor cells (NSTCs)." (PMID 34868955, 2021). "However, the levels of WDR12, but not of Pes1, were higher in high-grade gliomas than that in low-grade gliomas." (PMID 34868955, 2021).
Alzheimer disease (1 paper, 2024). A progressive, neurodegenerative disease characterized by loss of function and death of nerve cells in several areas of the brain leading to loss of cognitive function such as memory and language. "Many of these genes have been previously linked to brain-related disorders, including Alzheimer’s disease (WDR12, AGFG2, and CDK5RAP3), schizophrenia (SRA1, WDR55, CORO7, DDAH2, PCDHA8), autism spectrum disorder (MAPK3, PCDHA13), and major depressive disorder (ZMAT2 and ITIH4)." (PMID 39269986, 2024).
astrocytoma (1 paper, 2021). "The expression of WDR12 and Pes1 were both significantly upregulated in astrocytoma, oligodendroglioma, and GBMs compared to that in normal brains." (PMID 34868955, 2021).
cardiomyopathy (1 paper, 2015). A disease of the heart muscle or myocardium proper. "WDR12 protein was also found to be expressed in the LV of control human hearts and in patients with cardiomyopathy." (PMID 25915632, 2015). "In the present study we found that LV WDR12 expression was elevated in patients with cardiomyopathy, in rats post-infarction and in Ang II-mediated hypertension." (PMID 25915632, 2015). "Nuclear WDR12 protein levels were higher (1.8-fold) in patients with cardiomyopathy than in control hearts, and there was also a non-significant increase (2.1-fold) in total WDR12 protein levels in patients with cardiomyopathy when compared to control hearts." (PMID 25915632, 2015). "In our present study, nuclear WDR12 protein levels were elevated in LV of patients with cardiomyopathy, and there was also a non-significant increase in total WDR12 protein levels." (PMID 25915632, 2015). "Also WDR12 mRNA as well as ANP and BNP mRNA levels were higher in patients with cardiomyopathy (Data not shown)." (PMID 25915632, 2015).
colorectal cancer (1 paper, 2022). A primary or metastatic malignant neoplasm that affects the colon or rectum. "In addition to that, whole-genome gene expression profiling revealed WDR12 as an implicated gene in colorectal cancer." (PMID 36726716, 2022). "In colorectal cancer, WDR12 was found to be associated with tumor progression by promoting proliferation and inhibiting apoptosis where in-vivo tumor formation experiments in nude mice revealed that tumor area, volume, and weight were significantly lower for knockdown WDR12 (Fernández, 2014)." (PMID 36726716, 2022).
dilated cardiomyopathy (1 paper, 2015). Cardiomyopathy which is characterized by dilation and contractile dysfunction of the left and right ventricles. "LV WDR12 protein levels were increased in patients with dilated cardiomyopathy and rats post-infarction." (PMID 25915632, 2015).
heart failure (1 paper, 2015). Inability of the heart to pump blood at an adequate rate to meet tissue metabolic requirements. "On the other hand, no GWAS has so far identified genome-wide significant evidence for association between WDR12 variance and heart failure." (PMID 25915632, 2015).
hepatocellular carcinoma (1 paper, 2022). A malignant tumor that arises from hepatocytes. "Hepatocellular carcinoma was another type of tumor that experienced up-regulated expression of WDR12 where the knockdown of WDR12 expression resulted in reduced proliferation and migration of HepG2 and Huh-7 cells." (PMID 36726716, 2022).
Hypertension (1 paper, 2015). The presence of chronic increased pressure in the systemic arterial system. "Likewise, SERCA2 protein levels remained unchanged in WDR12-treated hearts post-infarction and in Ang II-mediated hypertension, whereas WDR12-induced impairment of LV systolic function was associated with the reduction of SERCA2 expressions in normal hearts." (PMID 25915632, 2015). "Effect of intramyocardial WDR12 gene delivery on cardiac structure and function in normal adult rat hearts, post-infarction, and in angiotensin II-induced hypertension at 1 week." (PMID 25915632, 2015). "LV WDR12 mRNA and protein levels at 1 and 2 weeks after WDR12 gene transfer post-infarction and in Ang II-mediated hypertension increased similarly to those observed in normal adult rat hearts (Data not shown)." (PMID 25915632, 2015). "The mechanisms for these distinct cardiac actions of WDR12 remain to be established, but may be due to diverse pathophysiological processes in MI and hypertension-induced heart disease." (PMID 25915632, 2015). "Because both MI and pressure overload caused significant up-regulation of WDR12 levels, we next examined the effects of WDR12 gene transfer on LV function and structure in MI induced by ligation of LAD and in angiotensin II-induced hypertension in rats." (PMID 25915632, 2015). "Remarkably, WDR12 overexpression consistently increased BOP1 in normal adult rat hearts (P<0.05), post-infarction (P<0.05), in Ang II-induced hypertension (P<0.05) and in vitro in neonatal rat cardiomyocytes (p = 0.061) and in cardiac fibroblasts." (PMID 25915632, 2015). "However, WDR12 gene delivery did not affect LV systolic function post-infarction or in Ang II-mediated hypertension." (PMID 25915632, 2015).
infarction (1 paper, 2015). A localised pathological necrosis of tissue resulting from obstruction of the blood supply usually by a thrombus, an embolus, or vascular torsion. "Because WDR12 was associated with early-onset MI in GWAS studies, we first assessed the effect of post-infarction remodeling process on LV WDR12 gene expression." (PMID 25915632, 2015). "The increase in LV WDR12 protein levels at 1 week after gene delivery closely mimicked those increases observed in rats post-infarction and in response to pressure overload." (PMID 25915632, 2015). "Strikingly, WDR12 gene delivery also affected LV diastolic function, as reflected by significantly decreased E/A ratio post-infarction." (PMID 25915632, 2015). "However, evaluation of diastolic function revealed that WDR12 gene transfer decreased E/A ratio by 32% (P<0.05) at 1 week post-infarction, suggesting that WDR12 gene delivery results in diastolic dysfunction." (PMID 25915632, 2015). "The present study shows that LV WDR12 mRNA and protein levels increase rapidly in response to cardiac overload (within 6–24 hours) suggesting that WDR12 may have a role in an early-phase remodeling process post-infarction and in pressure overload in rats." (PMID 25915632, 2015).
migraine (1 paper, 2023). "For example, of the five genes (CARF, ICAIL, NBEAL1, FAM117B, and WDR12) at the rs138556413 locus, ICAIL and NBEAL1 have the strongest TWAS p value with migraine as compared to other genes." (PMID 37245199, 2023).
cancer (5 papers, 2020 to 2025). A tumor composed of atypical neoplastic, often pleomorphic cells that invade other tissues. "We utilized the TCGA project and the publicly accessible bioinformatics tools to implement a pan-cancer analysis of WDR12 to examine the roles and underlying mechanisms of WDR12 in the pathophysiology or clinical prognosis of malignant tumors." (PMID 36726716, 2022). "WDR12 has been reported in several previous studies to be associated with cancer progression in several models of human tumors." (PMID 36726716, 2022). "Furthermore, significant correlations were found between WDR12 expression patterns and cancer-associated fibroblast (CAF) infiltration, myeloid-derived suppressor cells (MDSCs), tumor mutation burden, microsatellite instability and immunoregulators." (PMID 36726716, 2022). "WD repeat domain 12 (WDR12), a gene associated with cancer, serves essential roles in the pathway of ribosome synthesis." (PMID 39932915, 2025). "In related research, WDR12 has been identified as a potential biomarker across various human cancers, highlighting its significance in cancer research." (PMID 39434198, 2024). "Furthermore, it was discovered that TMB, MSI, and immunoregulators are associated with WDR12 expression in a subset of human cancers; therefore, these results potentially propose WDR12 as a prognostic biomarker of patients’ responsiveness to immunotherapy and a possible cancer treatment target." (PMID 36726716, 2022). "This was done to get a deeper insight into the relationship between WDR12 expression and the clinical outcome of cancer patients with various types of tumors." (PMID 36726716, 2022). "We performed a methylation data analysis to examine the possible correlation between WDR12 DNA methylation and the pathophysiology of various cancers." (PMID 36726716, 2022). "Furthermore, CpG aggregated methylation data showed that all significant findings favored hypomethylation of WDR12 in cancer tissues compared to normal samples (except for CHOL)." (PMID 36726716, 2022). "Aim of the study: This study aims to investigate the potential oncogenic effects of WDR12 in various human malignancies throughout a pan-cancer analysis that has been carried out to examine the various patterns in which this gene is expressed and behaves in tumor tissues." (PMID 36726716, 2022). "Finally, we investigated the functional characteristics of differentially regulated WDR12 by including WDR12-binding proteins in addition to WDR12 expression-related genes in all TCGA cancers, followed by KEGG pathway enrichment and GO enrichment analyses." (PMID 36726716, 2022). "Here, WDR12, MYC, WDR3, are critical in the regulation of cell cycle progression in cancer cells." (PMID 34131166, 2021). "Additionally, we used the GTEx dataset to further corroborate the expression profiles of WDR12 in a few more cancers that either did not have normal tissue matched in the TIMER2 dataset or had a small sample number (less than 20) of normal tissue that was used for expression comparison." (PMID 36726716, 2022).